ANXA5 (annexin A5)
Diseases named in the same sentence as ANXA5 in open-access papers (continued):
Sharing a sentence is not in itself a finding about the gene and the disease.
glioma (continued). "Differently, ANXA5 is regarded as a potential early biomarker in hepatocarcinogenesis together with ANXA2 and a predictive biomarker for tumor progression in different cancer types, but it was not so far identified as a specific oncogenic protein in gliomas as well as CAPZB and CAPZA1." (PMID 38607010, 2024).
ovarian carcinoma (101 papers, 2011 to 2025). A malignant neoplasm originating from the surface ovarian epithelium. "The further experiment suggests that Annexin A5 significantly regulates the signaling pathway involved in cell apoptosis on ovarian cancer." (PMID 32219016, 2020). "ANXA2/3/8/11 mRNA expression levels were significantly upregulated in ovarian cancer, and ANXA5/6/7 mRNA expression levels were significantly downregulated." (PMID 31474227, 2019). "Both databases showed that ANXA2, ANXA3, ANXA8, and ANXA11 mRNA expression levels were upregulated in ovarian cancer compared with normal tissues, while ANXA5,ANXA6, and ANXA7 mRNA expression levels were downregulated." (PMID 31474227, 2019). "We have previously created similar treatment for cancer based upon the NKG2D-ovarian cancer honing molecule or the Annexin A5 molecule, which showed the potential clinical applications and the importance of using antigen-specific immunotherapy to reverse immune tolerance." (PMID 35028321, 2022). "ANXA5 played a role in developing ovarian cancer, cervical cancer, and colorectal cancer." (PMID 36105100, 2022). "This evidence inspires us that the potential target of TPL effect on ovarian cancer cells could be Annexin A5." (PMID 32219016, 2020). "It was found that TOP2A, ANXA5, and LRRN4 were associated with ovarian cancer survival prognosis." (PMID 32368301, 2020). "Aberrant expression of ANXA5, CD81, and RAB5C affects the sensitivity of ovarian cancer cells to platinum- and paclitaxel-based chemotherapeutic agents." (PMID 37754253, 2023). "The results reveals that TPL markedly up-regulates the levels of Annexin A5 and ATP synthase proteins as well as down-regulates the levels of β-Tubulin and HSP90 in ovarian cancer cell lines." (PMID 32219016, 2020). "The results reveal that TPL markedly up-regulates the levels of Annexin A5 and ATP synthase proteins as well as down-regulates the levels of β-Tubulin and HSP90 in ovarian cancer cell lines." (PMID 32219016, 2020). "In addition, the expression levels of ANXA1, ANXA4, ANXA5, ANXA6, ANXA7 and ANXA13 were lower in ovarian cancer than in the normal controls." (PMID 31474227, 2019). "Therefore, ANXA5, CD81, and RAB5C may serve as therapeutic targets in drug-resistant ovarian cancer." (PMID 37754253, 2023).
colon carcinoma (92 papers, 2002 to 2025). "In this experimental study, OI with fluorescence-labeled Annexin A5 was investigated in a human colon carcinoma model in rats." (PMID 26393949, 2015).
prostate carcinoma (78 papers, 2011 to 2025). A carcinoma that arises from epithelial cells of the prostate gland. "In addition, ANXA5 knockdown induces phosphorylation of NF-κB p65 in prostate cancer cells, indicating that ANXA5 causes COX-2 downregulation through inhibition of p65 activation." (PMID 29088783, 2017). "In tumor cells, ANXA5 enhances the invasive ability of hepatocellular carcinoma cells and inhibits the expression of cyclooxygenase in prostate cancer cells." (PMID 40342928, 2025). "Prostate cancer cell fusion also depends on annexin A5, and its expression is increased in prostate cancer tissues compared with nonmalignant tissues." (PMID 33581114, 2021). "Human prostate cancer cells became fusiogenic after co-cultivation with muscle cells due to an IL-4 and IL-13 induced up-regulation of syncytin-1 and annexin A5." (PMID 34771528, 2021). "Previously, we found that auranofin induces expression of ANXA5 in human prostate cancer cells and triggers apoptosis." (PMID 29088783, 2017). "The invasion capacity of cancerous cells in oral carcinoma, prostate cancer has been shown to be partially regulated by annexin A5." (PMID 23717685, 2013). "Moreover, Annexin A5 (ANXA5) was found to promote prostate cancer stem cells, pancreatic adenocarcinoma, sarcoma and tumorigenesis and progression of BC." (PMID 37189694, 2023). "Moreover, ANXA5 has a broad distribution and has been observed to exhibit abnormal expression in various cancer types, such as prostate cancer, cervical carcinoma, and cholangiocarcinoma." (PMID 37660060, 2023). "Therefore, we anticipate that applying the anti-inflammatory effect of ANXA5 to prostate cancer therapy will have a better effect on inhibition of cancer development and improvement of drug resistance." (PMID 29088783, 2017). "Our results suggest that ANXA5 may act as a negative regulator for COX-2 expression by downregulating the PKC-ζ-NF-κB pathway in prostate cancer cells." (PMID 29088783, 2017). "Previously, we showed that auranofin induces ANXA5 in human prostate cancer PC-3 cells." (PMID 29088783, 2017). "We next determined whether the inhibition of COX-2 expression by auranofin was rescued by ANXA5 knockdown in prostate cancer cells." (PMID 29088783, 2017). "ANXA5 also has been reported to inhibit diffuse large B-cell lymphoma cell invasion and chemo-resistance, and the expression of ANXA5 may induce mitochondrial apoptosis in prostate cancer cells." (PMID 27684953, 2016). "In summary, we demonstrated that ANXA5 suppresses COX-2 expression via inhibition of NF-κB p65 phosphorylation, which is regulated by alteration of PKC-ζ protein levels in prostate cancer cells." (PMID 29088783, 2017). "In this study, we determined that inhibition of ANXA5 induces COX-2 expression in human prostate cancer cells and explored the correlation between PKC-ζ and ANXA5 on the regulation of COX-2 expression." (PMID 29088783, 2017). "Although there was no significant change in COX-2 mRNA and protein levels, ANXA5 overexpression inhibited COX-2 expression when cells were treated with TNF-α (20 ng/mL), which is known to induce COX-2 mRNA expression in various prostate cancer cells, including PC-3, LNCaP-LN3, and DU145." (PMID 29088783, 2017). "Unlike other prostate cancer cells, no noticeable alteration of PKC-ζ expression level by ANXA5 knockdown was observed in DU145 cells, which is similar to the pattern of COX-2 expression." (PMID 29088783, 2017).
cervical carcinoma (71 papers, 2008 to 2025). A carcinoma arising from either the exocervical squamous epithelium or the endocervical glandular epithelium. "Recent research findings indicate that overexpressed ANXA5 can inhibit the proliferation and metastasis of cervical cancer cells, thus exerting its anti-cancer gene function." (PMID 38724609, 2024). "Moreover, increased ANXA5 inhibits cervical cancer proliferation by regulating the expression of Bcl-2 and Bax." (PMID 36936694, 2023). "However, Annexin A5 expression is upregulated in a variety of cancers, such as hepatocarcinoma, cervical carcinoma, and squamous cell carcinoma, and plays roles in tumor development, invasion or metastasis." (PMID 36077467, 2022). "In cervical cancers, annexin A5 was higher at the protein level and suppressed at mRNA level." (PMID 35454982, 2022).
gastric cancer (69 papers, 2010 to 2025). A primary or metastatic malignant neoplasm involving the stomach. "To investigate the functional roles of ANXA5, we employed siRNA to diminish the expression of ANXA5 in two distinct human gastric cancer cell lines, achieving a significant knockdown efficiency as evidenced by RT-qPCR (P<0.001)." (PMID 40124374, 2025). "This implies that ANXA5 is involved in facilitating the proliferation of gastric cancer cells (P<0.001)." (PMID 40124374, 2025). "Collectively, these findings indicate that ANXA5 possesses a pro-tumorigenic function in gastric cancer, facilitating cell proliferation, invasion, and migration while inhibiting apoptosis." (PMID 40124374, 2025). "When the expression of ANXA5 was suppressed via siRNA, we noted a reduction in cell viability, an increase in apoptosis, and diminished migratory and invasive abilities of gastric cancer cells." (PMID 40124374, 2025). "At the cellular level, gastric cancer cell lines exhibited notably higher ANXA5 expression compared to normal gastric epithelial cell lines." (PMID 40124374, 2025). "This suggests a correlation between ANXA5 expression and the degree of differentiation of gastric cancer cells." (PMID 38287304, 2024). "Interestingly, however, another study highlighted ANXA5’s function as a gastric cancer tumor suppressor gene that inhibits the ERK signaling pathway, promising a supportive anticancer drug." (PMID 40124374, 2025). "Our experimental results show that ANXA5 is significantly overexpressed in gastric cancer." (PMID 40124374, 2025). "The results not only reinforce the role of ANXA5 as an oncogene in the development and progression of gastric cancer but also indicate that ANXA5 may act as a promising therapeutic target for the treatment of this cancer type." (PMID 40124374, 2025). "The results indicate that ANXA5 might influence the behavior of gastric cancer cells by modifying the concentrations of vital proteins important for apoptosis and cell adhesion." (PMID 40124374, 2025). "Finally, we carried out qRT-PCR analysis of the expression levels of RGS2, GNAI2, ANXA5, MARCKS, CD36, NRP1, and PDE4A in gastric cancer cells." (PMID 38274323, 2024). "Finally, we found that the imbalance of 11 immune regulatory factors could predict the overall survival time of gastric cancer, including EZH2, NRP1, CD59, OsBPL1aBCL11B, BASP1, HNMT, CXCR4, ASGR2, ANXA5, CDH2." (PMID 34322132, 2021). "Finally, Transwell assays revealed that the suppression of ANXA5 expression significantly impaired the migration and invasion capabilities of HGC-27 cells, suggesting that ANXA5 enhances the migratory and invasive characteristics of gastric cancer cells (P<0.001)." (PMID 40124374, 2025).
glioblastoma (68 papers, 2010 to 2025). The most malignant astrocytic tumor (WHO grade IV). "From the ROC results, it can be seen that ANXA5 is likely to be a promising target for chemotherapy of glioblastoma." (PMID 38724609, 2024). "The overexpression of ANXA5 increased the half maximal inhibitory concentration (IC50) values of temozolomide in glioblastoma multiforme cell lines, indicating its role in acquired drug resistance." (PMID 29443940, 2018). "Altogether, the investigation of exosome proteome derived from the U-87MG glioblastoma cells, and the changes in metastasis marker proteins such as hCG and annexin A5 under temperature stress, suggest a possibility that these proteins may be used as diagnostic markers." (PMID 27929413, 2016). "Meanwhile, it has been found that ANXA5 and ANXA2 could be used as independent prognostic biomarkers suggesting undesirable outcomes in glioblastoma." (PMID 40607003, 2025).
colorectal cancer (60 papers, 2013 to 2026). A primary or metastatic malignant neoplasm that affects the colon or rectum. "In colorectal cancer, ANXA5 overexpression reduces cell migration and downregulates EMT‐related genes, hindering metastasis." (PMID 39400959, 2024). "Meanwhile, the combination of epigallocatechin gallate and quercetin enhance ANXA5 to effectively inhibit colorectal cancer arrest at the G1 stage." (PMID 36936694, 2023). "We then evaluated the therapeutic antitumor efficacy of AnxA5-antigenic peptide fusion protein using the CT26 murine colorectal cancer model." (PMID 32111835, 2020). "In addition, ANXA5 has been shown to promote cancer in pancreatic, breast, and colorectal cancers." (PMID 40124374, 2025).
oral cancer (52 papers, 2012 to 2025). "Conversely, in some tumor cells such as oral carcinoma cells and murine hepatocarcinoma cells, as well as several normal cells including human keratinocytes and corneal epithelium, ANXA5 upregulation has increased cell migration, suggesting diverse effects of ANXA5 in different cell types." (PMID 37520464, 2023).
osteosarcoma (51 papers, 2012 to 2025). A usually aggressive malignant bone-forming mesenchymal neoplasm, predominantly affecting adolescents and young adults. "Additionally, the localization of ANXA5 in MG-63 osteosarcoma cells was determined using immunofluorescence microscopy, which revealed that ANXA5 was always strongly present in the nucleus with additional cytoplasmic staining." (PMID 40342928, 2025).
bladder cancer (50 papers, 2011 to 2025). "ANXA5 was mainly expressed in basal-squamous and neuronal types of bladder cancer." (PMID 34484309, 2021). "The prognostic value of ANXA5 is still ambiguous for DLBCL, although its downregulation appears as a poor prognostic marker with a high HR in bladder cancer." (PMID 36611989, 2023). "The expression of ANXA1, ANXA2, ANXA3, ANXA5, ANXA6, ANXA8, and ANXA13 was closely related to basal-subtype bladder cancer, while the expression of ANXA4, ANXA9, ANXA10, and ANXA11 was closely related to luminal-subtype BC." (PMID 34484309, 2021). "ANXA1, ANXA2, ANXA3, ANXA5, ANXA6, ANXA7, and ANXA9 had prognostic value in bladder cancer." (PMID 34484309, 2021). "We used TCGA data to find that in addition to ANXA1 and ANXA2, other ANXA family proteins (ANXA3, ANXA5, ANXA6, and ANXA9, which have not been studied) are also closely related to the prognosis of bladder cancer." (PMID 34484309, 2021).
hepatoma (40 papers, 2012 to 2025). "We constructed the prognostic risk score for patients with hepatocellular carcinoma as follows: risk score = (0.3519) × PPM1G + (0.0637) × FKBP1A + (0.0673) × STAM + (0.0373) × MAD2L2 + (0.0031) × TBL1XR1 + (0.0172) × ANXA5." (PMID 38049741, 2023). "Lastly, Anxa5 expression is upregulated early in the progression to hepatocellular carcinoma and here we demonstrate that t-TUCB-FLVs decreased its expression, suggesting potential anti-cancer activities of s-EH inhibition." (PMID 41007411, 2025). "In hepatocellular carcinoma, ANXA5 promotes cell migration, invasion and angiogenesis, correlating with poor prognosis." (PMID 39400959, 2024). "In vitro experiments showed that stable knockout of ANXA5 reduced the proliferation, migration, invasion, and lymph node adhesion of hepatoma Hca-P cells by inhibiting CD34 and VEGF3 increased the adhesion behavior between cells, and reduced tumorigenicity and malignant tumorigenesis in mice." (PMID 35992798, 2022). "Plate cloning and CCK8 experiments showed that the inhibition of STAM, ANXA5, and M2D2L2 expression significantly reduced the clonal formation and proliferation of hepatoma cells compared to the control group." (PMID 38049741, 2023). "Tropomyosin β chain, transgelin or annexin A5, with a lower expression in CM2- treated cells compared to CM1-treated cells, are down-regulated proteins in hepatocellular carcinoma." (PMID 22506042, 2012). "Additionally, ANXA5 and ANXA2 expressions were upregulated in advanced hepatocellular carcinoma stages which were proposed as potentially useful biomarkers for poor survival in liver cancer patients." (PMID 40607003, 2025). "In hepatocellular carcinoma, the overexpression of ANXA2, ANXA3, ANXA4, ANXA5 and ANXA11 promotes proliferation because ANXA2–ANXA5 affect Wnt/β-catenin, MEK-ERK, PI3K/AKT-HIF-α and other pathways." (PMID 36936694, 2023). "In previous findings, Annexin A5 (ANXA5) plasma levels were investigated as a potential biomarker for asthma diagnosis, pregnant and non-pregnant subjects, as well as for liver cirrhosis and hepatocellular carcinoma." (PMID 35884419, 2022).
neuroblastoma (40 papers, 2008 to 2025). Neuroblastoma (NB) is the most common solid, extracranial childhood tumor. "It has been observed that the ionomycin treatment of murine neuroblastoma cells results in translocation to the cell membrane of ANX, in the following order: ANXA2, ANXA4, ANXA6, ANXA1, ANXA5." (PMID 35207075, 2022).
lymphoma (33 papers, 2009 to 2025). A malignant (clonal) proliferation of B- lymphocytes or T- lymphocytes which involves the lymph nodes, bone marrow and/or extranodal sites. "Some of the studies that reported NUCB1 and ANXA5 as up-regulated analyzed the effects of anti-lymphoma drug combinations, such as R-CHOP/CHOP regimens and immunomodulatory agents, on chemo-sensitive or -resistant DLBCL patients’ samples and DLBCL cell lines." (PMID 36611989, 2023). "Interestingly, AnxA5 decreased apoptotic cell uptake by peritoneal macrophages, increased their uptake by DCs, and heightened the immunogenicity of irradiated lymphoma cells in vivo." (PMID 26915293, 2016). "On the other hand, AnxA5 counteracted apoptosis induced by etoposide (apoptosis inducing factor) and delayed the activation of caspase-3 in human CEM T-lymphoma cells." (PMID 31584984, 2019).
liver cancer (31 papers, 2009 to 2025). An epithelial or non-epithelial malignant neoplasm that arises from the liver. "Co-culturing human umbilical HUVEC with liver cancer cells HuH-7 of different ANXA5 expression levels revealed that overexpression of ANXA 5 in liver cancer cells enhances the tubulogenic ability of endothelial cells." (PMID 40342928, 2025). "The results revealed higher expression levels of STAM, ANXA5, and MAD2L2 in liver cancer cell lines compared to normal hepatocytes." (PMID 38049741, 2023). "The present study demonstrated that the expression levels of ANXA5, MAD2L2, and STAM in liver cancer cell lines were significantly higher than those in normal hepatocytes." (PMID 38049741, 2023). "In addition, in liver cancer cell lines MHCC97H, MHCC97L, and HCCLM3, which exhibited relatively high expression levels, we knocked down STAM, ANXA5, and MAD2L2 using siRNA and observed alterations in the biological functions of HCC cells." (PMID 38049741, 2023).